RN7SL644P (RNA, 7SL, cytoplasmic 644, pseudogene)
Gene: Miscellaneous RNA gene on chromosome 10 (92,659,044 to 92,659,302, forward strand). Ensembl gene ENSG00000264313.
Homologues: Orthologues: macaque Metazoa_SRP (90% identical). Paralogues in human: RN7SL596P (84% identical), RN7SL811P (84% identical), RN7SL96P (84% identical), RN7SL488P (84% identical), RN7SL391P (83% identical), RN7SL510P (83% identical), Metazoa_SRP (83% identical), Metazoa_SRP (82% identical), RN7SL134P (82% identical), RN7SL163P (82% identical), RN7SL784P (82% identical), RN7SL774P (81% identical), and 706 more.